RNU7-179P (RNA, U7 small nuclear 179 pseudogene)
Gene: Small nuclear RNA gene on chromosome 1 (15,608,078 to 15,608,145, reverse strand). Ensembl gene ENSG00000252417.
Homologues: Orthologues: chimpanzee U7 (100% identical), tropical clawed frog U7 (56% identical), tropical clawed frog U7 (54% identical), tropical clawed frog U7 (53% identical), tropical clawed frog U7 (51% identical), tropical clawed frog U7 (50% identical), tropical clawed frog U7 (49% identical), tropical clawed frog U7 (47% identical), tropical clawed frog U7 (46% identical). Paralogues in human: U7 (69% identical), RNU7-23P (66% identical), RNU7-26P (66% identical), RNU7-8P (66% identical), RNU7-21P (65% identical), RNU7-28P (65% identical), RNU7-40P (65% identical), RNU7-43P (65% identical), RNU7-1 (63% identical), RNU7-104P (63% identical), RNU7-13P (63% identical), RNU7-143P (63% identical), and 142 more.